HES6 (hes family bHLH transcription factor 6)
Description:
Does not bind DNA itself but suppresses both HES1-mediated N box-dependent transcriptional repression and binding of HES1 to E box sequences. Also suppresses HES1-mediated inhibition of the heterodimer formed by ASCL1/MASH1 and TCF3/E47, allowing ASCL1 and TCF3 to up-regulate transcription in its presence. Promotes cell differentiation (By similarity).
Synonyms: bHLHb41; C-HAIRY1; HES-6; bHLHc23
Tractability: No criterion of Open Targets' tractability assessment is met for any kind of drug.
Gene: Protein-coding gene on chromosome 2 (238,238,267 to 238,240,662, reverse strand). Ensembl gene ENSG00000144485.
Subcellular location: Nucleus
Subcellular location (Human Protein Atlas): Nuclear bodies; Cytosol
Gene Ontology:
Molecular function: protein binding; sequence-specific double-stranded DNA binding; DNA-binding transcription factor activity, RNA polymerase II-specific; RNA polymerase II cis-regulatory region sequence-specific DNA binding; RNA polymerase II-specific DNA-binding transcription factor binding; transcription regulator inhibitor activity; DNA binding; DNA-binding transcription factor activity; DNA-binding transcription repressor activity, RNA polymerase II-specific; protein dimerization activity; RNA polymerase II transcription regulatory region sequence-specific DNA binding
Biological process: anterior/posterior pattern specification; negative regulation of transcription by RNA polymerase II; positive regulation of transcription by RNA polymerase II; regulation of neurogenesis; regulation of DNA-templated transcription
Cellular component: chromatin; nucleus; transcription regulator complex
Genetic constraint (gnomAD): Loss-of-function variants: 26 observed, 10.87 expected, observed/expected ratio (o/e) 2.39. The synonymous counts are far from expectation, so gnomAD's model fits this gene poorly and the ratio says little. Missense variants: 355 observed, 245.83 expected, observed/expected ratio (o/e) 1.44, 90% interval 1.32 to 1.58. Synonymous variants: 159 observed, 109.09 expected, observed/expected ratio (o/e) 1.46, 90% interval 1.28 to 1.66.
Homologues: Orthologues: chimpanzee HES6 (98% identical), macaque HES6 (97% identical), dog HES6 (92% identical), pig HES6 (87% identical), rat Hes6 (86% identical), mouse Hes6 (86% identical), guinea pig HES6 (84% identical), zebrafish hes6 (54% identical), zebrafish her13 (50% identical), tropical clawed frog hes6 (48% identical), Drosophila melanogaster E(spl)mdelta-HLH (23% identical), Drosophila melanogaster E(spl)mgamma-HLH (21% identical), and 7 more. Paralogues in human: BHLHE41 (27% identical), BHLHE40 (27% identical), HEYL (25% identical), HEY1 (25% identical), HEY2 (24% identical), HES1 (24% identical), HES2 (24% identical), HES4 (23% identical), HES7 (23% identical), HES5 (21% identical), HELT (20% identical), HES3 (17% identical).
Diseases named in the same sentence as HES6 in open-access papers:
HES6 is named in the same sentence as 36 diseases in open-access papers, as found by Europe PMC text mining. Sharing a sentence is not in itself a finding about the gene and the disease. The quoted sentences say what the papers report.
prostate carcinoma (15 papers, 2009 to 2022). A carcinoma that arises from epithelial cells of the prostate gland. "We have found that HES6-driven genes are strongly associated with aggressive human prostate cancers at their presentation, demonstrating that this phenomenon is not confined to the laboratory setting or to cell lines alone." (PMID 24737870, 2014). "In the clinical setting, we have uncovered a HES6-associated signature that predicts poor outcome in prostate cancer, which can be pharmacologically targeted by inhibition of PLK1 with restoration of sensitivity to castration." (PMID 24737870, 2014). "Increased expression of HES6 has been detected in various tumors, including advanced astrocytoma, glioblastoma, prostate cancer, leukemia, gastric cancer, colon cancer, breast cancer, lung cancer, and kidney cancer and is associated with poor survival 37-41." (PMID 35673577, 2022). "HES6 also drives a critical AR transcriptional program to induce castration-resistant prostate cancer through the activation of an E2F1-mediated cell cycle network." (PMID 33681178, 2020). "Previous study shows that HES6 enhances prostate cancer aggressiveness in a Notch signalling independent way." (PMID 29050307, 2017). "In addition to the retina, post-translational regulation of Hes6 may occur elsewhere, given that Hes6 plays roles in late embryogenesis, myogenesis, and postnatal development, and its overexpression is linked to gliomas and breast and prostate cancer." (PMID 28036067, 2016). "We and others have shown that HES6 overexpression is sufficient to induce completely androgen independent growth in prostate cancer cells." (PMID 25749039, 2015). "We have recently identified a role for the enhancer of split transcription factor HES6 in prostate cancer and AR signalling." (PMID 25560400, 2015). "As shown by qPCR array, HES6 transcripts were approximately fourfold enriched in prostate cancer cells compared to benign prostate cells." (PMID 25864518, 2015). "Of note, HES6 has been recently reported to play an important functional role in prostate cancer enhancing oncogenic signalling through the AR." (PMID 25560400, 2015). "When engineered into prostate cancer cells, reduced levels of HES6 resulted in reduced cancer cell invasion and clonogenic growth." (PMID 25864518, 2015). "We found a significant decrease in HES6 expression in androgen-deprived cell lines and in prostate cancer specimens from patients treated with ADT." (PMID 25864518, 2015). "Our results confirm differential expression of Notch pathway members in aggressive prostate cancer and indicate a role for HES6, either by direct action or by activation of other pathways, in tumour progression." (PMID 25864518, 2015). "HES6 is a regulator of cell fate, either in normal development during neurogenesis and myogenesis 59,60, and establishment of neuroendocrine phenotype in prostate cancer." (PMID 25864518, 2015). "LnCaP and 22Rv1 prostate cancer cells have higher basal levels of HES6 expression than PC3, so we used HES6 knockdown in these cells to identify HES6 targets." (PMID 25864518, 2015). "Future studies will need to include overexpression of HES5 in prostate cancer cells to establish the direct consequences on HES6 and AR signalling, as well as the phenotypic consequences of bypassing HES5 silencing." (PMID 25560400, 2015). "We also examined HES6 regulation and function to help clarify its status in the Notch pathway and to further explore its role in prostate cancer." (PMID 25864518, 2015). "Our results also show that HES6 is the most highly induced putative Notch response gene in prostate cancer cells." (PMID 25864518, 2015). "To test the functional relevance of HES6 in the transition to CRPC, we stably overexpressed HA-tagged HES6 in androgen-sensitive prostate cancer LNCaP and DuCaP cells, which induced reduced sensitivity to bicalutamide." (PMID 24737870, 2014).
prostate carcinoma (continued). "We have identified HES6 as a transcription co-factor that is able to alter prostate cancer cell phenotype so fundamentally that these cells are able to grow in the absence of testosterone." (PMID 24737870, 2014). "This study demonstrates the relevance of HES6 in the development of androgen resistance and brings forward our understanding of how other factors co-operate with the master regulator of prostate cancer, the AR, to maintain essential pathways for cell survival." (PMID 24737870, 2014). "For instance, it was recently shown that Hes-6 and hASH-1 correlate with more-aggressive prostate cancer." (PMID 19891787, 2009). "Recently, Hes-6 and hASH-1 have been reported to be overexpressed in high-grade prostate cancer and were suggested to be involved in neuroendocrine development of the cancer cells to an aggressive phenotype." (PMID 19891787, 2009). "An up‐regulated expression of HES6, a helix–loop–helix transcriptional repressor, could significantly increase the invasive phenotype and decrease survival in prostate cancer and glioma." (PMID 35934844, 2022). "Moreover, enhanced HES6 expression stimulated the motile ability and invasive phenotype of prostate cancer cells, glioma cells and colorectal cancer cells 40,42,45." (PMID 35673577, 2022). "Thus, a prediction of the current studies is that the combined use of inhibitors of HES6 function, androgen withdrawal and strategies for gene re-expression, would synergise in preventing the growth of castration-sensitive prostate cancer." (PMID 32708551, 2020). "HES6 promotes cell proliferation and migration in some tumor such as glioma and prostate cancer." (PMID 29050307, 2017). "However, if RWPE-1 is excluded, Notch3 becomes the second most overexpressed gene in prostate cancer after HES6." (PMID 25864518, 2015). "HES6 knockdown influenced the expression of two cell migration-associated genes—metalloproteinase 7 (MMP7) and ITGB2 —as well as STEAP4, which was previously implicated in prostate cancer cellular proliferation." (PMID 25864518, 2015). "While the functional role of HES5 methylation in prostate tumourigenesis is yet to be determined, we found that demethylation resulted in downregulation of the HES5-target gene HES6, which has recently been shown to drive progression in prostate cancer via the androgen receptor." (PMID 25560400, 2015). "Our data also suggest that expression of Notch pathway members and of HES6 may be useful in distinguishing indolent from lethal prostate cancers." (PMID 25864518, 2015). "PC3 prostate cancer cells have relatively low basal levels of HES6." (PMID 25864518, 2015). "HES6 drives castration-resistant tumour growth by enhancing the transcriptional activity of the androgen receptor, while the Prolaris signature contains many genes known to be critical for cell cycle control—both processes already known to be essential for prostate cancer growth." (PMID 32708551, 2020). "Hedgehog signalling has been implicated in prostate cancer development, metastasis and androgen-independent growth 44,45, so repression of SUFU by HES6 could represent a new mechanism whereby prostate cancer cells induce hedgehog signalling to promote aggressive behaviours." (PMID 25864518, 2015). "However, the results do implicate HES6 as a promoter of prostate cancer progression." (PMID 25864518, 2015). "Compared to their more indolent counterparts, aggressive prostate cancer cells have been reported to up-regulate JAG2, Notch3 and the HES family member HES6 5,6." (PMID 25864518, 2015). "HES6, though homologous to Notch pathway targets, was unresponsive to NOTCH3–the Notch receptor most highly expressed in prostate cancer cells." (PMID 25864518, 2015). "Therefore, HES6 may play an important role in the plasticity of prostate cancer cells." (PMID 25864518, 2015).
prostate carcinoma (continued). "Treatment of prostate cancer cells with the demethylating agent 5-aza-2′-deoxycytidine increased HES5 expression and downregulated its transcriptional target HES6, consistent with functional silencing of the HES5 gene in prostate cancer." (PMID 25560400, 2015). "Although a rare HES6 gene fusion has been reported, no molecular mechanism has been found for the frequent up-regulation of HES6 in prostate cancer." (PMID 25560400, 2015). "As with previous studies that showed HES6 expression distinguishes metastatic from non-metastatic prostate cancers 6,40, these results strongly suggest that HES6 imbues cancer cells with the capacity to escape the prostate and generate metastatic clones." (PMID 25864518, 2015). "Despite the early and frequent silencing of HES5 in prostate cancer, we observed variable expression of the HES5 transcriptional target HES6 in prostate tumour samples, prompting us to investigate other factors that may regulate HES6 expression in prostate tumour cells." (PMID 25560400, 2015). "Such possibility was evidenced earlier in prostate cancer cells where another member of HES family, HES6, was regulated by androgens without involvement of Notch signaling." (PMID 32299422, 2020).
glioma (9 papers, 2014 to 2026). A benign or malignant brain and spinal cord tumor that arises from glial cells (astrocytes, oligodendrocytes, ependymal cells). "Applying TSProm to human brain, liver, and testis promoters, we identified clinically relevant transcription factors (TFs) in the brain, including SP1, MYC, and HES6, whose associations with gliomas and neuroblastomas highlight clinical relevance." (PMID 42244857, 2026). "Expression analysis indicates that HES6 co–factors are significantly upregulated in low-grade gliomas and glioblastomas of TCGA dataset, underscoring their critical role in brain cancer progression." (PMID 41279024, 2025). "Conversely, HES6 knockdown decreased the migration of glioma, glioblastoma, alveolar rhabdomyosarcoma and colorectal cancer cells 42,43,45." (PMID 35673577, 2022). "Transcriptomic analysis of glioma cells in which the expression of HES6 was reduced or enhanced revealed that the commonly dysregulated genes were associated with biological functions such as migration, invasion, cell-to-cell signaling and cell proliferation." (PMID 35673577, 2022). "Studies in colorectal cancers and glioma showed that HES6 represented a valuable prognostic biomarker 42-44." (PMID 35673577, 2022). "Bcor mutations have been found in AML, Itpka contributes to differentiation of human embryonic stem cells and is downregulated in oral squamous cell carcinoma, and Hes6 is overexpressed in glioma and breast cancer." (PMID 24944583, 2014). "Applying this framework to human brain, liver, and testis promoters, we identified and validated clinically relevant transcription factors (TFs) in the brain, including SP1, MYC, and HES6, and confirmed their known roles in diseases such as gliomas and neuroblastomas." (PMID 41279024, 2025). "Moreover, HES6 contributed to glioma cell proliferation and migration and had a role in angiogenesis." (PMID 33681178, 2020). "In glioma cells, NESTIN is one of the E-box-containing genes that increased after HES6 overexpression." (PMID 35673577, 2022). "Moreover, in glioma cells, HES1 was found to bind to a panel of HES6-regulated genes, and HES1 expression was reduced after HES6 downregulation." (PMID 35673577, 2022). "Despite these findings, RNA‐seq from a Nf1;Tp53CKO mouse model of glioma where the tumors also lack ASCL1 revealed that although some Notch related genes (Dll3, Hes5, Hes6) were decreased, expression of many of the Wnt related genes seemed unaffected by the loss of ASCL1." (PMID 32573857, 2020). "Thus, one could envision that in glioma cells, NOTCH1 mediates its effect through HES6 regulation, although this remains to be determined." (PMID 35673577, 2022).
breast carcinoma (7 papers, 2009 to 2024). "Because genetic abnormalities are common in breast cancer, it also is possible that the DNA regions harboring the Hes-6 gene are amplified in some breast cancer cells, thereby causing constantly increased Hes-6 levels." (PMID 19891787, 2009). "Hence, we examined the xenobiotic metabolism-associated genes (PYCR1, KYNU, CFB, HMOX1 and HES6) expressed in both breast cancer cells and in normal mammary epithelial cells." (PMID 37845207, 2023). "Because Hes-6 has been identified as a marker for aggressive, high-grade cancers of other origins than the breast, Hes-6 also could be associated with high proliferation and aggressiveness in breast cancer." (PMID 19891787, 2009). "Some other transcriptionally regulated targets of E2 that induce breast cancer cell proliferation are hes family bHLH transcription factor 6 (Hes-6), prostaglandin E synthase (PTGES), alkaline phosphatases (ALP) and the LRP16 gene, just to mention a few." (PMID 27160081, 2016). "Because Hes-6 is expressed at low levels in ERα+ breast cancer cells, we generated stable Hes-6-expressing T47D cells by lentiviral transduction with a Hes-6 expression vector." (PMID 19891787, 2009). "As expected, in parallel to the high levels of Hes-6, we identified a higher expression of E2F-1 in the breast cancer samples compared with that in the normal breast tissue samples, in agreement with what has been described by other researchers." (PMID 19891787, 2009). "Hes-6 is expressed in low levels in normal breast tissue but is strongly induced in breast cancer tissue." (PMID 19891787, 2009). "In breast cancer tissue, however, Hes-6 expression was increased by more than 28 times compared with that in normal breast specimens." (PMID 19891787, 2009). "Together, the data suggest that Hes-6 is a potential oncogene overexpressed in breast cancer, with a tumor-promoting and proliferative function." (PMID 19891787, 2009). "We therefore suggest that E2 treatment of ERα+ breast cancer cells leads to inactivation of Hes-1, both directly and through the induction of Hes-6." (PMID 19891787, 2009). "We first performed real-time PCR to determine Hes-6 mRNA levels in different breast cancer cell lines." (PMID 19891787, 2009). "In this study, we present evidence that Hes-6 has an important role in the proliferation of breast cancer cells and in the growth of corresponding xenografts." (PMID 19891787, 2009). "Based on our findings, we propose that Hes-6 has an important role in the proliferation of breast cancer cells." (PMID 19891787, 2009). "By expressing Hes-6 in the breast cancer cell-line T47D, we studied its role in tumor growth and proliferation." (PMID 19891787, 2009). "Last, estrogen-regulated HES6 enhances proliferation of breast cancer cells." (PMID 39545637, 2024). "Alternatively, it could mean that Hes-6 is induced in early stages of breast cancer and is important for the progression of breast cancer." (PMID 19891787, 2009). "Because Hes-6 antagonizes Hes-1, our hypothesis is that Hes-6 increases the proliferation of breast cancer cells and is regulated by estrogen." (PMID 19891787, 2009). "Hes-6 emerges as a potential marker for breast cancer and might be a target for novel treatments based on the Hes signaling pathway." (PMID 19891787, 2009). "An understanding of the role and regulation of Hes-6 could provide insights into estrogen signaling and endocrine resistance in breast cancer and, hence, could be important for the development of novel anticancer drugs." (PMID 19891787, 2009). "Further to study the function of Hes-6 in breast cancer cells and to determine whether Hes-6 influences tumor growth, we performed xenograft studies in SCID/beige-immunodeficient mice." (PMID 19891787, 2009). "Moreover, the level of Hes-6 mRNA was 28 times higher in breast cancer samples compared with normal breast samples." (PMID 19891787, 2009).